IL6 (interleukin 6)
Diseases named in the same sentence as IL6 in open-access papers (continued):
Sharing a sentence is not in itself a finding about the gene and the disease.
glioma (continued). "In addition, the influence of IL-6 signaling on the differentiation of C6 glioma cells has been mentioned elsewhere." (PMID 33227992, 2020). "Thus, it can be concluded that glioma secretes a large amount of IL‐6 into the peripheral circulation." (PMID 31599129, 2019). "Potentially, CBD-induced activation of IL6 expression in stress conditions might promote the viability and differentiation of a small population of glioma stem-like cells that were resistant to killing agents used." (PMID 30783513, 2019). "IL-6 is a pro-inflammatory cytokine that induces both the growth and invasiveness of gliomas." (PMID 31908585, 2019). "For IL‐6, five studies with 535 glioma patients were enrolled in the prognostic analysis." (PMID 31599129, 2019). "Five studies with 535 glioma patients were included in the prognostic analysis for IL‐6." (PMID 31599129, 2019). "Previously, our laboratory reported that there was a significant increase of multiple cytokines including interlukin-6 (IL-6) secreted in glioma-conditioned media from patient-derived adult GBM cell lines which suggested these tumors have increased STAT3 signaling." (PMID 31361777, 2019). "Moreover, miR-26a alleviated the inhibitory effect of AP-2α and the miR-26a inhibitor on glioma cells by upregulating the expression of Nanog/Sox2 and the IL6/Jak2/STAT3 signaling pathway." (PMID 31534499, 2019). "Moreover, our results indicated that increased circulating IL‐6, IL‐8, IL‐17, TNF‐α, TGF‐β, and CRP levels are significantly associated with increased glioma risk." (PMID 31599129, 2019). "Similarly, glioma associated human MSC increased proliferation and self-renewal of GSC in vitro and increased their in vivo tumorigenicity by secreting interleukin-6, which activates STAT3 in GSC." (PMID 29300332, 2018). "Immunoblot analysis confirmed that glioma-CM remarkedly increased IL-6 expression and moderately increased CSF-1 expression in ECs, and also showed that GBM-associated ECs constitutively expressed IL-6 and CSF-1 at a higher level than normal brain ECs." (PMID 29422647, 2018). "Among them, cytokines IL-6 and IL-8 activities are related to glioma progression." (PMID 29765540, 2018). "Besides acting by favouring immune-escape, they are also able to modify glioma cells by releasing IL6 and IL10." (PMID 29300332, 2018). "Importantly, analyses of TCGA and Rembrandt databases show that elevated IL-6 expression correlates with poor overall survival in glioma and GBM patients." (PMID 29422647, 2018). "The results indicated that the potent PKC inhibitor could prevent IL-6 upregulation and further destroy tubule formation of glioma cells." (PMID 27903982, 2017). "Moreover, IL6 generates an inflammatory microenvironment and promotes glioma stem-like cells (GSCs) survival and growth." (PMID 29258522, 2017). "We found that conditional medium derived from M2 amplified IL-6 expression in glioma cells." (PMID 27903982, 2017). "Taken together, these results indicated that IL-6 may play a significant role in M2-CM-enhanced VM in glioma cells." (PMID 27903982, 2017). "In order to determine whether there was a correlation of IL-6 upregulation with VM enhancement in glioma cells, IL-6 neutralizing antibody (anti-IL-6, 1 μg/ml) was used to investigate the effect of IL-6." (PMID 27903982, 2017). "IL6R overexpression or IL6 stimulation enhanced the invasion and growth of glioma cells." (PMID 29258522, 2017). "Selected examples: Exogenous IL-6 enhanced glioma cell migration in vitro." (PMID 28977822, 2017). "IL-6 also enhances neurosphere formation capacity and promotes the stemness of glioma CSCs." (PMID 28881826, 2017). "Furthermore, we found that hypoxia induced lncTCF7 expression in an autocrine manner through IL-6 in glioma." (PMID 29234033, 2017). "In addition, upregulation of both IL6 and IL6R was associated with decreased survival rates in both TCGA and REMBRANDT gliomas." (PMID 29258522, 2017).
glioma (continued). "Interestingly, IL-6 production by glioma cells was dramatically increased in the medium of M2-CM/U251 coculture system, compared to other groups." (PMID 27903982, 2017). "In this study, we further investigated the role and regulation of IL6 signalling in glioma." (PMID 29258522, 2017). "Interestingly, in the current study, cytokine array screened the potential key factor IL-6 which was the most significantly upregulated cytokine in glioma cells after stimulation by M2-CM." (PMID 27903982, 2017). "In all, these results indicated that the potent PKC inhibitor bisindolylmaleimide I could prevent M2-induced IL-6 upregulation and further inhibit tubule formation of glioma cells." (PMID 27903982, 2017). "A previous study demonstrated that as a stromal component of gliomas, mesenchymal stem cells could secrete IL6, which increased proliferation and maintained the stemness of GSCs." (PMID 29258522, 2017). "Indeed, addition of anti-IL6 inhibitory Ab (5 μg/ml) to the cell media significantly increased levels of apoptosis in glioma cells after treatment with CBD alone or in combination with γ-irradiation." (PMID 29088769, 2017). "IL6 may function as an autocrine and/or paracrine factor, and the high levels of IL6 in the glioma microenvironment could be the result of secretion by immune-infiltrating cells and stromal cells, in addition to tumour cells." (PMID 29258522, 2017). "Next, we sought to identify the regulatory factors involved in IL6 signalling in glioma cells." (PMID 29258522, 2017). "Importantly, we found that IL6-stimulated glioma growth and invasion was largely dependent on the expression of IL6R." (PMID 29258522, 2017). "Similarly, another glioma targeting ligand, I6P7, an interleukin-6 receptor binding peptide derived from IL-6, was included into a similar sequence defined carrier construct for glioma-targeted delivery of pDNA." (PMID 28963371, 2017). "In order to determine whether monocyte-derived M2 macrophages could promote VM through IL-6 upregulation in glioma cells, IL-6 transcription and concentration were determined by qRT-PCR and ELISA." (PMID 27903982, 2017). "Extensive hypoxic areas have been found in glioma tissues;45 however, the relationship between IL6 and the level of autophagy in the hypoxic areas of tumors remains unclear." (PMID 27163161, 2016). "IL-6 thus stimulated glioma cells through a paracrine mechanism in our model system." (PMID 27613828, 2016). "The results suggest that while IL-17 could influence cytokine secretion via regulation of IL-6 activity, it did also have distinct, IL-6-independent effect on cytokine secretion by gliomas." (PMID 26755664, 2016). "Furthermore, increased MMP14 expression correlated with IL-6 expression in primary human glioma specimens." (PMID 27613828, 2016). "Diverse immunomodulators and immunosuppressive factors are secreted by glioma cells, for example, interleukin-6 (IL-6) and colony stimulating factor-1 (CSF-1), which play an important role in Th2 response; this enhances its activity resulting in a less effective response against tumors." (PMID 27294132, 2016). "We thus hypothesized that IL-6 was also involved in regulating MMP14 expression through the activation of MMP2 or MMP9 in glioma." (PMID 27613828, 2016). "This work is significant because it characterizes the pivotal role of the IL6-p-STAT3-MIR155-3p pathway in hypoxia-induced autophagy in glioma cells, and this is the first demonstration of the therapeutic efficacy of IL6 receptor monoclonal antibody injection for the treatment of gliomas in vivo." (PMID 27163161, 2016). "Interleukin-6 (IL-6), one of the growth and survival cytokines involved in the modulation of immune and inflammatory responses, has been recently shown to promote invasion and migration of glioma cells." (PMID 27613828, 2016).
glioma (continued). "We found that the IL6 antibody exerted a suppressive effect on glioma cells in vitro by antagonizing hypoxia-induced autophagy and promoting apoptosis, suggesting that tocilizumab may inhibit glioma growth in vivo." (PMID 27163161, 2016). "Thus, glioma cells are clearly stimulated by strong IL6 signals in a complex hypoxic microenvironment." (PMID 27163161, 2016). "Multiple immunosuppressive factors are secreted by glioma cells, including IL6, which could polarize GAMs toward tumor-promoting M2 GAMs." (PMID 27163161, 2016). "Moreover, IL-6 activates several pro-proliferation and survival proteins in order to stimulate tumor cell growth; whereas, the inhibition of IL-6 signaling was shown to reduce both glioma size and aggressiveness." (PMID 27285760, 2016). "Moreover, we found that RTVP-1 regulated the mesenchymal transformation of both glioma cell lines and GSCs and that some of its effects were mediated by IL-6." (PMID 26267319, 2015). "We identified seven cytokines from previous glioma or allergy literature (IL4, IL13, IL5, IL6, IL10, IFNG and TGFB2) to determine whether, they were associated with glioma before diagnosis." (PMID 26352148, 2015). "We therefore focused on the role of the IL-6 pathway in RTVP-1 effects in glioma cells." (PMID 26267319, 2015). "We next examined whether the mesenchymal transformation of glioma induced by RTVP-1 was mediated by IL-6." (PMID 26267319, 2015). "Furthermore, VA has been shown to significantly inhibit LPS-induced production of TNF-alpha and IL-6 by human monocytic leukemia and glioma cells." (PMID 26317011, 2015). "Targeting IL-6 signaling suppresses glioma stem cell survival and cell growth." (PMID 26229239, 2015). "Using gene array analysis of RTVP-1 silenced glioma cells we identified IL-6 as a mediator of RTVP-1 effects on the mesenchymal transformation and migration of GSCs, therefore acting in a positive feedback loop by upregulating RTVP-1 expression via the STAT3 pathway." (PMID 26267319, 2015). "Moreover, treatment of glioma cells with IL-6 upregulated RTVP-1 expression and activation of the RTVP-1 promoter in glioma cells via activation of STAT3." (PMID 26267319, 2015). "The first hint that STAT3 may be involved in the aggressiveness of human gliomas was the discovery of an amplified expression of the Interleukin-6 (IL-6) gene in glioblastoma tissue samples and cell lines." (PMID 25268165, 2014). "Also, incubation of the glioma cells with recombinant IL-6 significantly increased their invasion, a process that was reversed with an IL-6 neutralizing antibody." (PMID 23864876, 2013). "The essential role of IL-6 in glioma development has been demonstrated in a mouse model." (PMID 22330721, 2012). "We have previously reported that IL-1β significantly induces IL-6 synthesis in C6 glioma cells." (PMID 21682888, 2011). "Therefore, the human glioma cell line U343 was selected for screening of IL-6-lowering effects of our in-house compound libraries." (PMID 21801384, 2011). "Therefore, the present study investigated which residue is involved in the TNF-α-stimulated IL-6 synthesis in C6 glioma cells." (PMID 20205746, 2010). "The hypothesis that activated macrophage/microglial cells may produce IL-6 through NF-κB and that glioma cells, particularly tumor stem cells, may be activated by IL-6 through a paracrine mechanism deserve further studies." (PMID 24281089, 2010). "The IκB-NFκB pathway is involved in TNF-α-induced IL-6 release from C6 glioma cells." (PMID 20205746, 2010). "Tumor necrosis factor (TNF)-α induces IL-6 release from rat C6 glioma cells through the inhibitory kappa B (IκB)-nuclear factor kappa B (NFκB) pathway, p38 mitogen-activated protein (MAP) kinase and stress-activated protein kinase (SAPK)/c-Jun N-terminal kinase (JNK)." (PMID 20205746, 2010). "In gliomas, IL-6 plays a role in promoting tumour growth and angiogenesis." (PMID 17224923, 2007).
glioma (continued). "In gliomas, the level of IL-6 gene expression increases with the grade of malignancy." (PMID 17224923, 2007). "Notably, IL-6 gene amplification was associated with significantly shorter survival times compared to glioma patients without amplification." (PMID 40143164, 2025). "Of note, IL-6 deficient mice developed normally, thus IL-6 could be pivotal in glioma pathogenesis but does not appear to be essential for normal growth and development." (PMID 39512605, 2024). "Furthermore, IL-6 treated glioma cells could upregulate the expression of RTVP-1 and enhance the RTVP-1 promoter activity by activating STAT3." (PMID 36923251, 2023). "However, various oncogenic processes or signals in PRAME-positive gliomas such as E2F targets, G2M mitotic checkpoint, reactive oxidative oxygen species, IL6-JAK-STAT6, angiogenesis, epithelial-mesenchymal transition, and mTORC1 were activated at the lower levels compared to PRAME-negative tumors." (PMID 37796789, 2023). "Furthermore, CENP-A may contribute to glioma progression through the regulation of pathways, including the cell cycle, nucleosome assembly, IL6-JAK-STAT3 signaling, and DNA repair." (PMID 36105094, 2022). "Indeed, IL6 signaling through STAT3 is required for glioma development in a preclinical model." (PMID 36046049, 2022). "Moreover, FTY720, a potent immunosuppressant, may be potentially used to inhibit glioma growth by inhibiting MAPK-mediated secretion of IL-6 following increased internalization of CXCR4." (PMID 36555253, 2022). "As suggested in other types of cancer, the reduction of PBDCs in our patients may be sustained partly by DC recruitment into the tumor microenvironment, and partly by tumor-derived cytokines, such as VEGF and IL-6 that are produced by glioma cells and inhibit DC maturation in the bone marrow." (PMID 36703985, 2022). "Macrophages are recruited to the glioma environment to create a supportive stroma for glioma cell proliferation, survival, and migration through immune functions, such as the release of transforming growth factor-β, epidermal growth factor, interleukin (IL)-6, and IL-1β." (PMID 34660294, 2021). "Furthermore, IRF7 depletion could suppress glioma progression and decrease cellular heterogeneity in vivo through interleukin-6 and Notch signaling." (PMID 33902005, 2021). "By exploring the B7-H4 level in glioma tissues with different grades, Yao and their colleagues found that the cross-talk between glioma-initiating cells and macrophages mediated by B7-H4 through the IL6/JAK/STAT3 pathway could result in poor prognosis." (PMID 33539322, 2021). "Next, we investigated whether IL6 autocrine signaling could affect cancer cell stemness in glioma." (PMID 33576874, 2021). "In addition, overexpression of TMEM44-AS1 increased the IL-6 expression in SF126 glioma cells." (PMID 34696771, 2021). "Besides its general pro-inflammatory function, IL6, which is a widely-distributed cytokine in the nervous system, is critically important for glial differentiation of normal neural precursor cells and adult glioma differentiation of glioma stem-like cells." (PMID 30783513, 2019). "Furthermore, the circulating IL‐6 or CRP level may be a reliable prognostic indicator in glioma patients." (PMID 31599129, 2019). "Finally, although we conducted subgroup analyses for IL‐6, IL‐8, IL‐10, and TNF‐α with glioma risk to explore the potential sources of heterogeneity, high heterogeneity still existed in the studies of IL‐4, IL‐12, IL‐17, IL‐23, TGF‐β, and MCP‐1 based on the limited number of included studies." (PMID 31599129, 2019). "In addition, the risk score was also positively associated with the expression of INF-γ, IL-6, CCL2 and HLA-A, suggesting that macrophages and T cell mediated immune response were involved in high-risk group of glioma patients." (PMID 30407923, 2018).
glioma (continued). "In glioma tissues, only low amounts of the M1-associated pro-inflammatory cytokines IFN-γ, TNF-α, IL-2, and IL-12 were detected, while high amounts of M2-associated anti-inflammatory cytokines such as TGF-β, IL-6, and IL-10were found in these tumors, indicating an immunosuppressive TME." (PMID 29389898, 2018). "Besides, it has been demonstrated that IL-6 promoted VEGF-induced glioma angiogenesis." (PMID 27903982, 2017). "Therefore, IL6R of the tumour cells might be a better target than IL6 for the potential novel treatment of gliomas." (PMID 29258522, 2017). "In addition, the potent PKC inhibitor bisindolylmaleimide I could prevent M2-induced IL-6 upregulation and further inhibited glioma VM facilitation." (PMID 27903982, 2017). "Furthermore, our data indicated that IL-6 could promote glioma VM, as blocking IL-6 with neutralizing antibodies abrogated M2-mediated VM enhancement." (PMID 27903982, 2017). "Moreover, high HMGA2 expression levels correlate with shorter survival time in glioma patients using the CGGA (The Chinese Glioma Genome Atlas) dataset, which is consistent with reports showing higher levels of IL-6/HMGA2/SOX2 expression indicated shorter overall survival period in GBM patients." (PMID 27259253, 2016). "The results indicated that knockdown of IL6 and MIR155-3p could inhibit tumor growth in vivo by blocking autophagy and inducing apoptosis in glioma cells, confirming the central role played by the IL6-p-STAT3-MIR155-3p pathway in controlling hypoxia-induced autophagy." (PMID 27163161, 2016). "We first examined whether IL-6 can induce mesenchymal transformation of glioma cells." (PMID 26267319, 2015). "Interleukin 6 (IL-6) treatment significantly upregulated HCMV gene expression in long-term infected glioma cultures, suggesting that pro-inflammatory signaling in the tumor milieu may further augment HCMV gene expression and subsequent tumor progression driven by viral-induced cellular signaling." (PMID 25549333, 2014). "TNF‐α/NF‐κB signaling is another key inflammatory axis: TNF‐α can stimulate glial and immune cells to produce IL‐6 and activate NF‐κB, which in turn sustains STAT3 signaling, thereby enhancing glioma cell proliferation and aggressiveness." (PMID 41354084, 2025). "All three collectively contribute to a pro-tumorigenic glioma TME, despite IL-10 being anti-inflammatory and IL-1β and IL-6 being pro-inflammatory." (PMID 41157253, 2025). "On the other hand, studies have demonstrated that IL-6 and TNF-α contribute to glioma cell proliferation, invasion, and migration." (PMID 40149846, 2025). "As expected, the conditioned medium from either GL261 or ALTS1C1 glioma cells significantly activated BV2 cells with a notable increase in pro-inflammatory cytokines, including IL-6, CCL-2, CXCL-10, MMP-14, TNFα, IL-1β, and iNOS." (PMID 41367876, 2025). "Microglia-derived cytokines and chemokines, particularly PDGFB, EGF, SDF-1α, IL-6, and IL-8, activate Pyk2, but only PDGFB, EGF, SDF-1α and IL-6 promote Pyk2-related glioma cell invasion and proliferation." (PMID 40867240, 2025). "This study systematically explored for the first time the combined effect of AVP, OT, β-EP and serum inflammatory factors (TNF-α, IL-6, CRP) in postoperative nerve injury and prognosis of patients with glioma, filling the research gap in this field." (PMID 41244525, 2025). "Its activation, often triggered by tumor-associated microglia and macrophages derived cytokines such as EGF, IL-6, and SDF-1α, promotes a tumor-supportive microenvironment by enhancing glioma cell motility, invadopodia activity, and cell cycle progression." (PMID 40867240, 2025).